CDH13 (cadherin 13)
Diseases named in the same sentence as CDH13 in open-access papers (continued):
Sharing a sentence is not in itself a finding about the gene and the disease.
esophageal cancer (3 papers, 2018 to 2021). A primary or metastatic malignant neoplasm involving the esophagus. "Hypermethylation of CASZ1, CDH13 and ING2 genes detected using cell-free DNA in blood samples can be applied as a potential biomarker for the diagnosis of esophageal cancer." (PMID 30355852, 2018). "Hypermethylation of CASZ1, CDH13 and ING2 detected in plasma cell-free DNA can be applied as a potential noninvasive biomarker for diagnosis of esophageal cancer." (PMID 30355852, 2018).
glioblastoma (3 papers, 2015 to 2026). The most malignant astrocytic tumor (WHO grade IV). "Ca13Mab-17 also detected endogenous CDH13 in human glioblastoma (LN229 and U87MG) and lung mesothelioma cell lines." (PMID 42200830, 2026).
invasive breast carcinoma (3 papers, 2014 to 2026). A carcinoma that infiltrates the breast parenchyma. "Cadherin-13 (CDH13), a tumor suppressor gene, exhibits methylation linked to increased metastatic potential and reduced tamoxifen sensitivity in invasive breast carcinomas." (PMID 41123022, 2026). "The dataset included uterine corpus endometrial carcinoma (UCEC), Breast invasive carcinoma (BRCA), and cervical squamous cell carcinoma and endocervical adenocarcinoma (CESC) and showed a significant down-regulation of CDH13." (PMID 39179585, 2024).
lung adenocarcinoma (3 papers, 2016 to 2025). A carcinoma that arises from the lung and is characterized by the presence of malignant glandular epithelial cells. "While for instance APC and CDH13 methylation was detected more frequently in lung adenocarcinomas compared to lung squamous cell carcinomas, p16 methylation was detected more frequently in lung squamous cell carcinomas than in lung adenocarcinomas." (PMID 28093071, 2017). "With higher occurrences, the correlation of differential gene expression and aberrant DNA methylation of AGR2, CDH13, and MX2 have been reported relevant to lung adenocarcinoma." (PMID 27610367, 2016).
lymph node metastasis (3 papers, 2004 to 2014). "For lymph node metastasis, ten CpGs from six genes were found to be significant: CDH1 (site 10), CDH13 (sites 7 and 8), MINT3 (sites 3 and 4), CXCL12 (sites 1 and 3), RARB (site 6) and APC (sites 1 and 6)." (PMID 25052224, 2014). "CDH13 and RIL (PDLIM4) expression levels were significantly decreased in lymph node metastasis, whereas no significantly changes in the expression of RASSF1A, RARβ2 and CDH1 mRNAs were observed." (PMID 20642860, 2010).
myocardial infarction (3 papers, 2011 to 2025). Gross necrosis of the myocardium, as a result of interruption of the blood supply to the area, as in coronary thrombosis. "We identified seven CNV regions that were associated significantly with hyperlipidemia and myocardial infarction in our patients through multistage analysis (P<0.001), at 1p21.3, 1q31.2 (CDC73), 1q42.2 (DISC1), 3p21.31 (CDCP1), 10q11.21 (RET) 12p12.3 (PIK3C2G) and 16q23.3 (CDH13), respectively." (PMID 22369086, 2011).
neuroblastoma (3 papers, 2004 to 2025). Neuroblastoma (NB) is the most common solid, extracranial childhood tumor. "β-Amyloid-treated SH-SY5Y neuroblastoma cells displayed a robust rise in CDH13 mRNA and protein levels, accompanied by a pronounced drop in endogenous miR-377." (PMID 40649905, 2025). "A previous study demonstrated that expression of Cdh13 in neuroblastoma cells resulted in their inability to respond to epidermal growth factor-induced proliferation, indicating it functions as a negative regulator of neuronal cell growth." (PMID 28386779, 2017).
substance abuse (3 papers, 2012 to 2022). The use of a drug for a reason other than which it was intended or in a manner or in quantities other than directed. "CDH13 has previously been associated with a number of substance abuse and other psychiatric phenotypes and is also supported by data from knock-out mice." (PMID 22952603, 2012).
type 2 diabetes (3 papers, 2017 to 2022). "CDH13 may serve as an adiponectin receptor and has been associated with plasma adiponectin and the risk of type 2 diabetes." (PMID 36585686, 2022).
Cognitive impairment (2 papers, 2021 to 2024). Abnormal cognition is characterized by deficits in thinking, reasoning, or remembering. "Thereby, CDH13 might contribute to important symptomatic domains of cognitive impairment and disturbed social relationships in ADHD." (PMID 34573337, 2021). "Thus, CDH13 might contribute to symptomatic core dysfunctions of social and cognitive impairment in ADHD." (PMID 34573337, 2021). "Considering the synapticlocalization of PCDH9, CDH13 and PCDH19, a mismatch in expression could alter the synaptic contactadhesion leading to network dysfunction and cognitive impairment, both of which arefeatures of PCDH19-CE pathology." (PMID 38629124, 2024).
COVID-19 (2 papers, 2024 to 2025). A disease caused by infection with severe acute respiratory syndrome coronavirus 2. "Variants on the CDH13 gene associated with COVID-19 risk of death were recently reported in a European population." (PMID 38791465, 2024). "Our results are in line with a recent genome-wide association study performed in a multi-center of European COVID-19 patients, which identified nine single nucleotide polymorphisms (SNPs) in the CDH13 locus on chromosome 16, associated with COVID-19 risk of death." (PMID 38791465, 2024). "Results confirmed that cadherin-13 was significantly decreased (p < 0.05) in the plasma of severe COVID-19 patients compared to healthy controls in our cohort." (PMID 38791465, 2024). "Our validation results showed that COVID-19 patients had lower plasma levels of cadherin-13 in a severity-dependent manner and reached statistical significance in the severe group." (PMID 38791465, 2024). "Therefore, the decreased levels of cadherin-13 found in the severe COVID-19 patients by proteomics and ELISA cannot be attributed to cardiovascular disease but to an increased severity of COVID-19." (PMID 38791465, 2024). "In addition, our results suggest that COVID-19 patients with cardiovascular disease in our population may be more likely to develop severe disease due to COVID-19-induced depletion of cadherin-13 levels." (PMID 38791465, 2024). "The decrease of cadherin-13 in COVID-19 patients has not been reported before, suggesting that it could be a Puerto Rican-specific immune response to SARS-CoV-2." (PMID 38791465, 2024). "Consequently, T-cadherin emerges as a pivotal molecular hub, yet the link between CDH13 gene and COVID-19 symptoms has not been investigated so far." (PMID 40109358, 2025).
head and neck squamous cell carcinoma (2 papers, 2021). A squamous cell carcinoma that arises from any of the following anatomic sites: lip and oral cavity, nasal cavity, paranasal sinuses, pharynx, larynx, and salivary glands. "We previously showed that p-EMT genes such as SERPINE1, ITGA5, TGFBI, P4HA2, CDH13, and LAMC2 are potent poor prognostic markers in head and neck squamous cell carcinoma (HNSCC) patients by bioinformatic analysis." (PMID 34294795, 2021).
ischemia (2 papers, 2021 to 2025). A hypoperfusion of the BLOOD through an organ or tissue caused by a PATHOLOGIC CONSTRICTION or obstruction of its BLOOD VESSELS, or an absence of BLOOD CIRCULATION. "Under nonischemic conditions, pericytes expressed Cdh19, Cdh6, Cdh10, Cdh4, Cdh13, and Cdh5; after ischemia, the cadherin genes that were predominantly expressed were Cdh15, Cdh11, Cdh3, and Cdh2." (PMID 33726849, 2021).
malaria (2 papers, 2016 to 2021). Malaria is a serious and sometimes fatal disease caused by a parasite that commonly infects a certain type of mosquito which feeds on humans. "In contrast, two of the random SNPs that had highly significant correlations (P < 0.01) were in genes previously linked to malaria resistance, namely, CDH13, encoding cadherin 13, and HS3ST3B1, encoding heparan sulfate 3-O-sulfotransferase 3B1." (PMID 26744416, 2016). "A second gene among the top 1% random loci that has been previously implicated as malaria protective was CDH13 (rs8048962, r = 0.64, P = 0.0013, fig." (PMID 26744416, 2016). "Genes with top scores encode for different malaria relevant functions such as regulation of inflammation (CSMD1), neural adhesion (CNTN4, PCSK5, CDH13, TMEM132), vascular epithelial development (FLT4), and protein kinases (PTPRT, PRKG1)." (PMID 34868193, 2021). "Two of these (CDH13 and HS3ST3B1) have previously been shown to be malaria-associated and both are involved in glycoprotein-mediated cell-adhesion pathways that are widely implicated in the pathogenesis of malaria." (PMID 26744416, 2016).
oesophageal cancer (2 papers, 2004). "Compared with CDH13-unmethylated cancers, CDH13-methylated cancers showed a trend towards preferentially invasive (P=0.140) and short time alive (P=0.167) in oesophageal cancers." (PMID 15292927, 2004).
preeclampsia (2 papers, 2013 to 2025). Preeclampsia is a hypertensive disorder of pregnancy that is characterized by new-onset hypertension with proteinuria presenting after 20 weeks of gestation, and depending on mild or severe forms may initially present with severe headache, visual disturbances, and hyperreflexia. "Third, while we limited our study to only one genetic variant of CDH13, future studies should evaluate associations between preeclampsia and other genetic variants, particularly those that lack strong linkage disequilibrium with rs11646213." (PMID 23976997, 2013). "First, genetic factors that influence the pathogenesis of preeclampsia differ by ethnic group, and the association between CDH13 and preeclampsia need to be confirmed in a larger sample size composed of different ethnic groups." (PMID 23976997, 2013). "Based on the close association between adiponectin and preeclampsia, it is rational to speculate that CDH13 may be involved in the pathogenesis of preeclampsia through interactions with adiponectin." (PMID 23976997, 2013). "Rs11646213 upstream of the CDH13 gene is associated with preeclampsia in Han Chinese women." (PMID 23976997, 2013). "Similarly, the differential expression of vascular regulators such as IGFBP7 and CDH13 points to sex-specific differences in angiogenic regulation, a key aspect of placental development and preeclampsia pathophysiology." (PMID 41444673, 2025). "Second, the functional significance of the SNP rs11646213 remains unknown and molecular mechanisms regarding CDH13 in the pathophysiology of preeclampsia should be examined in future studies." (PMID 23976997, 2013). "Cadherin-13 plays an important role in many biological processes, including vascular wall remodeling, modulating angiogenesis and protecting endothelial cells from oxidative stress-induced apoptosis, most of which are involved in the pathogenesis of preeclampsia." (PMID 23976997, 2013). "Although late-onset preeclampsia is not as strongly associated with placental vascular dysfunction as early-onset preeclampsia, genes such as CP, IGFBP7, CDH13, ROBO1, UNC5C, NRXN3, and ITGA1 suggest subtle changes in angiogenic pathways." (PMID 41444673, 2025).
pulmonary fibrosis (2 papers, 2022 to 2025). Chronic progressive interstitial lung disorder characterized by the replacement of the lung tissue by connective tissue, leading to progressive dyspnea, respiratory failure, or right heart failure. "Third, employing Cdh13−/− mice, we unveiled the protective role of T-cadherin deficiency against bleomycin-induced lung fibrosis." (PMID 40109358, 2025). "Furthermore, through experiments involving Cdh13−/− mice, we demonstrated that T-cadherin deficiency confers protection against bleomycin-induced lung fibrosis." (PMID 40109358, 2025). "By day 28 post-bleomycin exposure, Cdh13−/− mice exhibited significantly reduced lung fibrosis compared to control WT mice (p < 0.0001, Mann-Whitney)." (PMID 40109358, 2025). "Cdh13−/− mice displayed considerably diminished lung fibrosis compared to the controls." (PMID 40109358, 2025).
Adenomatous Polyposis Coli (1 paper, 2019). "Compared with adjacent normal tissues, tumor samples exhibited hypermethylation of Estrogen Receptor 1, Cadherin 13, Retinoic Acid Receptor Beta, Cell Surface Adhesion Molecule, and Adenomatous Polyposis Coli (ESR1, CDH13, RARB, IGSF4, and APC) genes." (PMID 31390840, 2019).
ANCA)-associated vasculitis (1 paper, 2021). "Recently, it was shown that T-cadherin (cadherin-13) content in platelet-derived microparticles changes in acute phase of antineutrophil cytoplasmic antibody (ANCA)-associated vasculitis." (PMID 33808741, 2021).
astrocytoma (1 paper, 2004). "Demethylation mediated inducible expression of the CDH13, MAGEA1, MGMT, p73 and RASSF1A genes was established in an astrocytoma cell line (U251), demonstrating that expression of these genes is likely regulated by DNA methylation." (PMID 15367334, 2004).
bladder transitional cell carcinoma (1 paper, 2020). The most common morphologic subtype of urinary bladder carcinoma (over 90% of cases). "Downregulation of CDH13 expression promotes invasiveness of bladder transitional cell carcinoma." (PMID 32922663, 2020).
chronic obstructive pulmonary disease (1 paper, 2017). A chronic and progressive lung disorder characterized by the loss of elasticity of the bronchial tree and the air sacs, destruction of the air sacs wall, thickening of the bronchial wall, and mucous accumulation in the bronchial tree. "The CDH13 polymorphisms play critical roles in metabolic processes and in the development of metabolic-related diseases and lung diseases such as chronic obstructive pulmonary disease." (PMID 28355295, 2017).
diffuse gastric cancer (1 paper, 2024). "CDH13 is interesting also in the context that another gene in the same family, CDH1, is responsible for familial early onset diffuse gastric cancer." (PMID 39543761, 2024).
drug dependence (1 paper, 2012). "The association between CDH13 and sensitivity to the subjective effects of amphetamine may provide insight into the mechanism by which an allele influences the risk for drug dependence." (PMID 22952603, 2012).
emphysema (1 paper, 2014). "We found higher levels of CDH13 to be associated with CT-assessed emphysema in the COPDGene cohort, but these were not available for validation in the TESRA cohort." (PMID 25306249, 2014). "The study confirms a previously identified association between radiologic emphysema and sRAGE, builds on data suggesting a role for ICAM1 as a biomarker, in addition to discovering previously not identified biomarkers associated with emphysema such as CCL20, cadherin 1, cadherin 13 and SERPINA7." (PMID 25306249, 2014). "CDH13 or H cadherin is another adhesion molecule that may influence surfactant protein D levels and serum adiponectin levels, both implicated in the pathogenesis of COPD; however, CDH13 itself has not been associated with quantitative emphysema to date." (PMID 25306249, 2014). "Cadherin 13 (CDH13) and thyroxin-binding globulin (SERPINA7) were positively correlated with emphysema severity (p < 0.001 for all comparisons)." (PMID 25306249, 2014). "Other biomarkers such as CHD1, CDH13 and SERPINA7 may also have a role in evaluating emphysema (especially milder emphysema), although require confirmation in other cohorts." (PMID 25306249, 2014).
Epileptic encephalopathy (1 paper, 2021). A condition in which epileptiform abnormalities are believed to contribute to the progressive disturbance in cerebral function. "Both CDH13 and PCDH9 have an intronic deletion and a duplication, respectively, and both have been associated to epileptic encephalopathy." (PMID 33557955, 2021).
gallbladder cancer (1 paper, 2016). "A previous study showed that ZEB1 suppresses the expression of CDH13 (T-cadherin) in gallbladder cancer cells." (PMID 27818995, 2016).
granulosa cell tumor (1 paper, 2022). A slow-growing, malignant tumor, characterize by the presence of granulosa-like cells and Call-Exner bodies, that is almost always found in the ovary. "Although Cdh13 expression and function are associated with ovary development and granulosa cell tumors, the meaning of its late expression here and the apparent inhibition by CIS and LH is undetermined." (PMID 35406774, 2022).
hypopharyngeal cancers (1 paper, 2018). Carcinoma, predominantly squamous cell, arising from the epithelial cells of the hypopharynx. "Notably, the less frequently methylated genes (less than 30%) were as follows: CDH13, p16, MGMT, GAL, NPY, GALR2, and VEGFR3 for hypopharyngeal cancers; CDH13, p16, RASSF1A, GAL, NPY, and NPY1R for laryngeal cancers; and CDH13 and GAL for oral cavity cancers." (PMID 29361757, 2018).
invasive carcinoma (1 paper, 2015). A carcinoma that is not confined to the epithelium, and has spread to the surrounding stroma. "Notably CDH4 is a critical regulator of epithelial phenotype and CDH13 levels are frequently down regulated in invasive carcinoma cells." (PMID 26151554, 2015).
invasive ductal adenocarcinoma (1 paper, 2025). "They observed frequent promoter hypermethylation of BRCA2, CDH13, MSH6, PAX5, PAX6, and WT1 genes in both DCIS and adjacent invasive ductal adenocarcinoma lesions." (PMID 40131297, 2025).
keratoconus (1 paper, 2020). A degenerative, structural disorder of the eye, characterized by a cone-shaped protrusion of the cornea. "Specifically, we selected seven keratoconus-susceptibility genes (CDH13, SMAD3, ADAM12, CSMD1, NRXN1, CPLX2, and WWOX) for further analysis." (PMID 32737415, 2020).
methamphetamine dependence (1 paper, 2012). A drug dependence that is a psychological dependency on the regular use of methamphetamine. "We identified several putative associations; the strongest was between a positive subjective drug-response factor and a SNP (rs3784943) in the 8th intron of cadherin 13 (CDH13; P = 4.58×10−8), a gene previously associated with a number of psychiatric traits including methamphetamine dependence." (PMID 22952603, 2012).
microtia (1 paper, 2024). "The verification of the multi-omics results with other microtia patients identified that ALDOB, ADIPOQ, CDH13 and TASP1, and oxidative stress may play a role in chondrogenic anomalies." (PMID 38802922, 2024). "This is coherent with the result in IHC that CDH13 and ADIPOQ are lower in microtia patients." (PMID 38802922, 2024).
muscular dystrophy (1 paper, 2022). Muscular dystrophy (MD) refers to a group of more than 30 genetic diseases characterized by progressive weakness and degeneration of the skeletal muscles that control movement. "Interestingly, the expression of the myogenic markers cadherin-13 (CDH13) and CD34 were both elevated in muscular dystrophy." (PMID 36362832, 2022).
myeloproliferative neoplasm (1 paper, 2011). A clonal hematopoietic stem cell disorder, characterized by proliferation in the bone marrow of one or more of the myeloid (i.e., granulocytic, erythroid, megakaryocytic, and mast cell) lineages. "CDH13, PGR-A and B isoforms were identified by a genome wide screening as hypermethylated in patients with myeloproliferative neoplasms." (PMID 21760961, 2011).
Osteopenia (1 paper, 2020). Osteopenia is a term to define bone density that is not normal but also not as low as osteoporosis. "Thus, CDH-13 could have therapeutic potential as a protein drug for the prevention of osteopenia." (PMID 32396872, 2020).
osteoporosis (1 paper, 2020). A condition of reduced bone mass, with decreased cortical thickness and a decrease in the number and size of the trabeculae of cancellous bone (but normal chemical composition), resulting in increased fracture incidence. "Since the inhibition of RANKL has long been recognized as a therapeutic strategy for osteoporosis, our findings suggest that CDH-13 could be used as a novel therapeutic molecule to inhibit bone loss." (PMID 32396872, 2020).